CTLA4 (cytotoxic T-lymphocyte associated protein 4)
Diseases named in the same sentence as CTLA4 in open-access papers (continued):
Sharing a sentence is not in itself a finding about the gene and the disease.
colitis (continued). "In this analysis emergence of CTLA4 antibody induced colitis in patients treated with HD IL-2 following ipilimumab was seen, consistent with a prior report from the National Cancer Institute." (PMID 27660706, 2016). "Toxicities observed on HD IL-2 were relatively equivalent between the groups although there were cases of CTLA4 antibody-induced colitis reported after HD IL-2 treatment and a CTLA4 antibody-induced colitis related death." (PMID 27660706, 2016). "We show here that the differential effects of iTregs depending on the effector subsets, and that CTLA4 is critically involved in both processes, inhibition of Th1/Th2-mediated colon inflammation and stimulation of Th17-mediated colon inflammation." (PMID 26950218, 2016). "Colonoscopy with biopsy revealed diffuse active colitis with moderate inflammation in the mid sigmoid colon consistent with CTLA4 antibody-related colitis." (PMID 27660706, 2016). "A major problem in CTLA-4 blockade therapy is the development of potentially life-threatening IRAE like colitis, hepatitis, alveolitis and hypophysitis." (PMID 26196012, 2014). "These defects are associated with altered IL-10, CTLA4, GITR and CD103 expression in PP4-deficient Treg cells, and are accompanied by gut inflammation and spontaneous colitis in the CD4cre:PP4f/f mice." (PMID 24904742, 2014). "Accordingly regulation of colitis by wildtype Treg can be blocked by anti-CTLA-4 antibody, but CTLA-4-deficient Treg can instead utilize IL-10 to achieve regulation." (PMID 23849743, 2013). "We found that CTLA4-Ig completely prevented colitis and very efficiently cured established disease, indicating a central role of T-cell costimulation in the model." (PMID 22536543, 2012). "Collectively, we found that CTLA4-Ig, anti-IL-12p40 mAb, and antibiotics prevented onset of colitis and cured established disease, while anti-TNF-α mAb, anti-IL-6 mAb, and anti-α4β7 mAb prevented onset of colitis but did not reverse established disease." (PMID 22536543, 2012). "The CD4+FoxP3+CD103+ subset expresses CTLA-4; suppresses T cell proliferation in vitro; and protects mice from colitis in the severe combined immunodeficient (SCID) transfer model in vivo." (PMID 21966415, 2011). "Whilst CTLA-4 blockade results in a plethora of immune adverse reactions including potentially fatal colitis, the sustained overall response in 20.8% of patients at 3 years provides an impetus to investigate the use of this agent in the adjuvant setting." (PMID 22220281, 2011). "Notwithstanding these caveats, we speculate that the disequilibrium imposed on CTLA4 following USP8 deletion may contribute to the colitis phenotype." (PMID 39404738, 2025). "Colitis and adrenal insufficiency, which were observed more frequently among patients who experienced AEs of grade 3 and higher, were distinctive findings of the anti‐CTLA‐4 antibody." (PMID 40249663, 2025). "Relapse of colitis occurred in 4/23 rechallenged patients (17.4%) after a median time of 9.5 weeks (IQR 7.5–27.5 weeks) including the only patient treated with anti-PD1 + anti-CTLA-4 upon rechallenge." (PMID 41156090, 2025). "Moreover, dual targeting of cytotoxic T-lymphocyte-associated protein 4 (CTLA-4) and PD-1, alongside clinically available TNF inhibitors, enhances macrophage depletion and prevents colitis and hepatitis in vivo." (PMID 40725144, 2025). "In addition, the use of clinically available TNF inhibitors in combination with CTLA-4 and PD-1 immunotherapy in mice has been found to alleviate colitis and improve anti-tumor efficacy." (PMID 40797218, 2025). "A cross-sectional study of clinical and pathological data analyses from patients with anti-CTLA-4/PD-1 colitis demonstrated that CD8+TRMs constituted the majority of activated TRMs in irColitis, with the degree of activation correlating with clinical and endoscopic severity." (PMID 40165945, 2025). "We observed induction of Ctla4 in the colon in both innate immune mediated models of colitis." (PMID 39496592, 2024).
colitis (continued). "Similarly, the incidence of colitis is higher with CTLA-4 inhibitors (5.7–39.1%) compared to PD-1/PD-L1 inhibitors (0.7–31.6%)." (PMID 39451777, 2024). "In addition, exogenous supplements of probiotics such as Bifidobacterium and Lactobacillus were also confirmed to ameliorate the DSS plus anti-CTLA-4 colitis in murine model." (PMID 38243343, 2024). "In that analysis, colitis was the most common cause of death arising from an irAE in patients receiving anti-CTLA-4 antibodies (135 of 193 deaths (70%)), and the combination of anti-CTLA-4 and anti-PD-1 antibodies increased the incidence and severity of irAEs." (PMID 38791528, 2024). "We, next, investigated whether this pro-inflammatory gene expression in the innate immune compartment, following genetic deletion or antibody blockade of CTLA-4, had a disease immunological phenotype by using three different colitis models." (PMID 39496592, 2024). "In addition, immune-related adverse reactions, including colitis, hepatitis, dermatitis, thyroiditis, and hypophysitis, have been reported in over 60% of patients receiving CTLA-4-based immunotherapies." (PMID 38791528, 2024). "Moreover, histologically pathologic features of anti-PD-1/PD-L1 therapy-related colitis were distinct from anti-CTLA-4 therapy." (PMID 38243343, 2024). "Histologically, diffuse active colitis patterns may be seen with CTLA-4 inhibitors and lymphocytic and collagenous colitis patterns may be seen with pembrolizumab." (PMID 39727645, 2024). "Combination therapy with PD-1 and CTLA4 monoclonal antibodies (e.g., nivolumab combined with ipilimumab) has been approved, though it has been observed to synergistically increase side effects such as colitis." (PMID 38713378, 2024). "Notably, CTLA-4 and PD-1 inhibitors have been reported to exhibit different irAE profiles; colitis and hypophysitis are more common with the former, and pneumonitis and thyroid abnormalities are more common with the latter." (PMID 38668043, 2024). "However, when the CTLA-4-driven regulatory circuit is lost, unopposed mucosal immune activation leads to colitis development." (PMID 39496592, 2024). "Notably, the severity of fatal organ involvement varies across anti-CTLA-4 and anti-PD-1/PD-L1 interventions, with colitis being the most commonly observed in the former and neurotoxicity, hepatitis, and pneumonitis being recorded in the latter." (PMID 38165484, 2024). "Findings from selective depletion of CD4+ and CD8+ T cells or the use of IFNγ‐neutralizing antibodies in ICB‐driven colitis indicated that CD4+ T‐cell‐mediated responses and IFNγ are primarily responsible for the intestinal inflammation caused by CTLA‐4 blockade." (PMID 38881673, 2024). "Hence, further researches are required to thoroughly examine the cumulative effects and the underlying mechanisms of T‐cell CTLA‐4 inhibition and the depletion of Tregs by anti‐CTLA‐4 antibodies during colitis." (PMID 38881673, 2024). "Common irAEs for CTLA-4 ICIs are colitis, pituitary gland inflammation, and rash." (PMID 37727216, 2023). "Colitis, hypophysitis and rash were common in patients treated with CTLA4 inhibitors." (PMID 36765782, 2023). "Furthermore, some cancer patients with CTLA-4 treatment-related colitis showed high serum concentrations of IL-17, and a preclinical animal study further confirmed this finding and found that CTLA-4 blockade promoted Th17 T cell differentiation." (PMID 36831664, 2023). "The type of fatal irAEs varied depending on the regimen; the most common fatal irAE with anti-CTLA-4 treatment was colitis (70%), whereas the most common fatal irAEs with anti-PD-1/anti-PD-L1 treatment were pneumonitis (35%), hepatitis (22%), and neurotoxicity (15%)." (PMID 36600271, 2023).
colitis (continued). "In the context of a colitis-permissive intestinal microbiota, combination of immune checkpoint blockade with anti-CTLA4 and anti-PD-1 results in the emergence of IL23-dependent, polyfunctional, cytolytic, CD4+ and CD8+ T-cell responses that are functionally important in CPI colitis development." (PMID 37872166, 2023). "However, skin, hepatic, and pulmonary-related irAEs are more frequent in the case of anti-PD1 antibody administration than anti-CTLA4 antibodies, it is the opposite for thyroid and lower digestive tract irAEs, such as colitis." (PMID 37445336, 2023). "There is also a difference in the organ specificity of adverse events, for example, colitis, hypophysitis and skin rashes occur more frequently with CTLA-4 inhibitors, while pneumonia, hyper- or hypo-thyroidism, joint pain and vitiligo are more common with PD-1 inhibitors." (PMID 36769093, 2023). "The therapeutic efficacy of CTLA-4-blocking agents, such as ipilimumab and tremelimumab, varies among patients and is often accompanied by the development of autoimmune side effects, including colitis." (PMID 38055819, 2023). "In addition, colitis occurred much earlier in CTLA-4 inhibitor-containing regimens than in non-CTLA-4 inhibitor-containing regimens (median duration: 28 days vs. 157 days, P=0.019; median immunotherapy cycles: 2 cycles vs. 8 cycles, P=0.015)." (PMID 38090496, 2023). "However, one can consider switching from an anti-CTLA-4 to an anti-PD-1/PDL-1, given the decreased risk of colitis with anti-PD-1/anti-PDL-1 agents." (PMID 37476113, 2023). "CTLA4 targeted therapy was found to result in the development of interstitial pneumonia, glomerulonephritis, renal vasculitis, sialadenitis and rarely cases of hepatitis, colitis, gastritis, and arthritis with varying severity in each group." (PMID 37259163, 2023). "mediated IL-10 and IL-22 production in a DSS-driven model of anti-CTLA-4-mediated colitis." (PMID 36622383, 2023). "Notably, cancer patients treated with anti-CTLA4 antibodies have increased penetrance and severity of colitis than patients treated with anti-PD-1 antibodies." (PMID 37872166, 2023). "Colitis could occur at any time after the commencement of ICIs, with an earlier occurrence with PD-1 inhibitors, but a greater severity with anti-CTLA-4 and, especially, with combination therapy." (PMID 37511260, 2023). "Colitis is a common irAE seen with both anti-CTLA-4 and anti-PD-1 antibodies and may be severe or life-threatening." (PMID 37298653, 2023). "Similarly, Lactobacillus reuteri administration inhibits the progression of ICI-associated colitis in mice administered DSS in their drinking water and treated with anti-CTLA-4 and anti-PD-1 immunotherapy." (PMID 36713364, 2022). "For example, colitis appears faster following anti-CTLA-4 and slower after anti-PD-1 therapy." (PMID 35327411, 2022). "Two patients with a CTLA4-insufficiency had colitis: IBD-like and lymphocytic colitis." (PMID 34599484, 2022). "Colitis and hypophysitis often occur in patients receiving CTLA4 inhibitors, while less common AEs (pneumonitis and thyroiditis) may occur in patients using drugs targeting PD-1/PD-L1 pathway." (PMID 36159789, 2022). "Also, in murine models of colitis and allergy-induced inflammation, increased expression of ICOS and CTLA-4 on Tregs was associated with immune suppression." (PMID 35819849, 2022). "Anti-CTLA-4-induced colitis presents at a median time of onset 4 weeks after first infusion." (PMID 35474500, 2022). "Colitis is more commonly seen with anti-CTLA-4 monotherapy than with anti-PD-1/PD-L1 inhibitors." (PMID 35015209, 2022). "TNF-α is highly expressed in intestinal mucosa with CTLA-4-induced colitis." (PMID 36189293, 2022). "Additionally, nearly half of all patients treated with the combination of anti-CTLA-4 and anti-PD-L1 antibodies develop colitis, and anti-CTLA-4 therapy at a high dosage causes colitis more frequently than low-dose therapy." (PMID 35740355, 2022).
colitis (continued). "For example, gastrointestinal (colitis) and endocrine toxicity (hypophysitis, adrenal insufficiency, hypopituitarism) were more preferentially reported with anti-CTLA-4, whereas thyroid dysfunction, pneumonitis and myocarditis were more frequently recorded with anti-PD-1/PD-L1." (PMID 35431928, 2022). "Colitis was the most frequent AEs in combination therapy with CTLA-4." (PMID 36612259, 2022). "Pretreatment with vancomycin induced a much earlier onset and more severe anti-CTLA-4-induced colitis in mice, whereas Bifidobacterium administration could ameliorate colitis without affecting the anticancer response." (PMID 34217349, 2021). "Organ-specific irAEs differed between the two agents; anti-PD1 treatment was complicated more frequently with arthritis, pneumonitis, myocarditis, thyroiditis and hematologic toxicities, whereas anti-CTLA4-driven toxicities included colitis, hypophysitis and skin rash." (PMID 34208218, 2021). "Regarding PD-1/PD-L1 inhibitors, dermatologic toxicity is the most reported and diarrhoea and colitis may be the most clinically relevant irAE in CTLA-4 inhibitors therapy, which have also led to death." (PMID 33650838, 2021). "For example, abatacept is effective in patients with CTLA4 deficiency, as seen in a patient in our study, and HCT is known as a therapeutic option for treatment of XIAP, CGD, and IL-10 deficiency and associated IBD-like colitis." (PMID 34456911, 2021). "Within the 34 cases that received an immunomodulatory agent, the vast majority (23/34) of the toxicities were associated with anti-CTLA4/anti-PD1 and included colitis grade ≥2 (n = 13), hepatitis grade ≥3 (n = 5), arthritis grade ≥2 (n = 3), gastritis grade 3 (n = 1) and pneumonitis grade 2 (n = 1)." (PMID 34208218, 2021). "Interestingly, a recent study demonstrated that TNFα inhibitors concomitantly with combined anti-PD-1 and anti-CTLA-4 antibodies improved immune related colitis in addition to enhanced anti-tumor efficacy." (PMID 33571254, 2021). "In this study, we found that treatment with rTsPmy significantly increased the expression of TIGIT within CD4+Foxp3+ T cells and the proportion of CTLA4+Foxp3+ Treg cells in CD4+ T cells in mice with colitis compared with mice with colitis that received PBS only." (PMID 34336843, 2021). "Another finding suggesting a fundamental difference in IBD and ICI-induced colitis is that serum from patients with anti-CTLA-4-induced colitis has fluctuating levels of antibody titers against microbial flora while these titers are characteristically altered in classic IBD." (PMID 33923423, 2021). "In keeping with this hypothesis the prevalence of colitis as adverse effect in cancer patients receiving PD-1 blockade is much lower than in patients receiving anti-CTLA-4 therapy." (PMID 34421921, 2021). "Moreover, recent research illustrated distinct immunological features of colonoscopy from CIC and IBD patients, with predominantly CD4+ T cells and Treg cells in the anti-CTLA-4-induced colitis and IBD patients, respectively." (PMID 34992611, 2021). "In the monotherapy regimens, anti-PD1 treatment was mostly associated with skin (vitiligo-like depigmentation 12.2%, rash 9.5%) and endocrinological (thyroiditis 19%, hypophysitis 9.5%) toxicities, whereas colitis (34.7%) and skin rash (22.4%) were commonly observed in single-agent anti-CTLA4." (PMID 34208218, 2021). "Interestingly, this study also showed a higher number of B-lineage cells in UC compared to the anti-CTLA-4-induced colitis group." (PMID 33923423, 2021). "For instance, the injection of anti-CTLA-4 mAb was shown to ameliorate trinitrobenzene sulfonic acid (TNBS)-induced colitis by increasing indoleamine 2,3 dioxygenase (IDO) expression and inducing IL-10-producing ICOS+ Treg expansion in the mesenteric lymph nodes and inflamed colon." (PMID 32983168, 2020).
colitis (continued). "The increase in circulating IL-17 levels, which are usually inhibited by CTLA-4, might be a reflection of patients with subclinical colitis, but ICI intervention disrupts this ecological balance." (PMID 33317597, 2020). "This study demonstrates that Tα1 protects mice from anti–CTLA-4–induced colitis and sustains its antitumor activity, thus suggesting that Tα1 may be used in combination protocols." (PMID 32817121, 2020). "Colitis is one of the most common irAEs related to anti-CTLA-4 immunotherapy." (PMID 32183814, 2020). "Meanwhile, the response of mice to anti-CTLA4 antibody could be restored and the degree of immune-mediated colitis could be significantly reduced by taken orally administration of Bacillus fragilis and Bacillus cepacia." (PMID 33488618, 2020). "Colitis is more common during treatment with anti–CTLA-4 antibodies." (PMID 32294888, 2020). "Recent study has revealed that the role of Bifidobacterium in mitigating autoimmune toxicities without compromising treatment efficacy, whereas vancomycin pre-treatment to mice with colitis and treated with anti-CTLA-4 therapy results in more severe and fatal manifestation of colonic inflammation." (PMID 32514151, 2020). "This hypothesis is supported by data showing that anti-CTLA-4-induced and anti-PD-1-induced colitis are eminently different in their immune cell composition, suggesting a distinct underlying mechanism for these toxicities." (PMID 33643899, 2020). "We found that blocking T cell homing increased colitis severity in the context of CTLA-4 blockade and that gut-trafficking blockade had different effects on different Th subsets and could facilitate the proliferation of Th17 cells in the lamina propria (LP)." (PMID 32183814, 2020). "We next used a model of colitis where Tregs have a well-documented role in suppressing colonic inflammation in order to better understand the relative impact of anti-CTLA4 Fc effector function versus CTLA4 blockade on Treg activity." (PMID 33127658, 2020). "Moreover, the immune stimulatory effect of anti-CTLA-4 blockade reactivated T-cells, which resulted in anti-cancer response, but also immune-mediated colitis." (PMID 31450659, 2019). "Cases of grade 3+ colitis often imply permanent discontinuation of anti-CTLA-4 therapy." (PMID 31293970, 2019). "In addition, in vivo models for colitis and diabetes demonstrate the importance of CTLA-4 for the Treg inhibitory function." (PMID 31474984, 2019). "The most common GI toxicities reported from anti-CTLA-4 ICIs are diarrhea and colitis." (PMID 31293970, 2019). "This indicates that increased levels of circulating IL-17 may be reflective of patients with subclinical colitis, the development of which would be normally inhibited by CTLA-4." (PMID 31192215, 2019). "Vancomycin pre-treatment worsened the colitis provoked by CTLA-4 blockade in mice." (PMID 29789015, 2018). "For these reasons, regulatory cells and receptors are likely to play a central role in maintaining the gut barrier and GI toxicities, such as colitis and hepatitis are indeed among the most common side effects of CTLA-4 blockade and to a lesser extent blockade of PD-1 and PD-L1." (PMID 29230210, 2017). "The most important radiologic manifestations of irAE induced by anti-CTLA-4 and anti-PD-1 antibodies may include colitis, hepatitis, pancreatitis, hypophysitis, pneumonitis, arthritis and sarcoid-like lymphadenopathy." (PMID 28959504, 2016). "However, physicians administering HD IL-2 following ipilimumab should be aware of possible anti-CTLA4- related colitis exacerbation following HD IL-2 therapy since diarrhea is a common symptom with both HD IL-2 and ipilimumab treatment." (PMID 27660706, 2016). "Care should be taken to avoid reactivation of CTLA4 antibody-induced colitis." (PMID 27660706, 2016). "The frequency of colitis in patients receiving CTLA-4 blockade could be explained, in part, by the T-regulator depletion induced by this treatment." (PMID 26337719, 2015).